WNT3A (Wnt family member 3A)
Diseases named in the same sentence as WNT3A in open-access papers (continued):
Sharing a sentence is not in itself a finding about the gene and the disease.
liver fibrosis (5 papers, 2014 to 2025). "Elevated Wnt3a expression has been reported in both carbon tetrachloride (CCl4)-induced hepatic fibrosis models and schistosomiasis-induced hepatic fibrosis models in mice." (PMID 40496021, 2025). "Our study found that the expression of Wnt genes (Wnt1, Wnt2, Wnt3, Wnt3a and Wnt5a) was upregulated, and Wnt pathway signalling in hepatocytes was active during the progression of schistosomiasis-induced liver fibrosis." (PMID 28331224, 2017). "The results showed that the over expression of Wnt3a exacerbates liver fibrosis, and intervention with DKK1 ameliorates the liver fibrosis." (PMID 28331224, 2017). "Liver fibrosis was exacerbated when exogenous Wnt3a was introduced, but was alleviated when Wnt signalling was suppressed by DKK1, accompanied by the reduced expression of TGF-β and CTGF in hepatocytes." (PMID 28331224, 2017). "Wnt4 is known to contribute to renal fibrosis, and Wnt3a and Wnt5a are involved in lung and liver fibrosis respectively." (PMID 24747916, 2014). "Therefore, we established a lentiviral vector loaded with either Wnt3a mRNA or Dkk1 mRNA and used them as transfected viruses to investigate the effects of the canonical Wnt pathway on schistosomiasis-induced liver fibrosis." (PMID 28331224, 2017). "This study was the first to validate the reduction in BMSCs in rat liver fibrosis and found that BMSC treatment exerted antifibrotic effects by activating the expression of GSK3β and inhibiting the Wnt3a/β-catenin signalling pathway." (PMID 35440002, 2022). "Both hBM-MSCs and hBM-MSCs-Ex treatment significantly inhibited the expression of PPARγ, Wnt3a, Wnt10b, β-catenin, WISP1, Cyclin D1, α-SMA, and Collagen I in both HSCs and liver fibrosis tissues (p < 0.005, p < 0.001)." (PMID 30885249, 2019). "In addition, we found that hBM-MSCs-Ex inhibited the expression of Wnt/β-catenin pathway components (PPARγ, Wnt3a, Wnt10b, β-catenin, WISP1, Cyclin D1), α-SMA, and Collagen I, in both HSCs and liver fibrosis tissue." (PMID 30885249, 2019).
lymph node metastasis (5 papers, 2019 to 2025). "Wnt3a expression was positively correlated with lymph node metastasis and clinical stages and negatively associated with poor prognosis, indicating their potential value in the surveillance of cancer progression and prognosis." (PMID 31111621, 2019). "Univariate Cox regression analyses showed that primary tumor site, clinical stage, T classification, lymph node metastasis, and Wnt3a protein were significantly associated with OS (All P < 0.05)." (PMID 31528227, 2019). "Furthermore, when correlated with clinicopathological characteristics, Wnt3a expression level was substantially associated with the patient’s prognosis, tumor stage, and lymph node metastasis." (PMID 38806610, 2024). "When stratified survival analyses were performed, patients with lymph node metastasis/advanced clinical stages and high Wnt3a expression had worse OS rates than patients with other features (P < 0.001)." (PMID 31528227, 2019). "In conclusion, this is the first study to explore the prognostic value of Wnt3a protein in LSCC and found that the upregulated expression of Wnt3a protein is a predictor of multiple cancer malignant processes such as histological grade, advanced clinical stage, and lymph node metastasis." (PMID 31528227, 2019). "Our results demonstrated that Wnt3a expression was higher in LSCC tissues than that in normal tissues, and that it was also significantly associated with histological grade, clinical stages, and lymph node metastasis." (PMID 31528227, 2019). "Finally, we found that high Wnt3a expression was an independent adverse prognostic factor for overall survival, especially when combined with advanced clinical stage and lymph node metastasis status." (PMID 31528227, 2019). "High expression of Wnt3a was closely related to histological grade (P = 0.031), clinical stage (I+II / III+IV; P = 0.004), and lymph node metastasis (P = 0.03)." (PMID 31528227, 2019). "Univariate and multivariate analyses indicate that Wnt3a is an independent prognostic factor in patients with LSCC and is a useful biomarker for assessing lymph node metastasis and prognosis in patients with LSCC." (PMID 31528227, 2019). "Clinical tissue samples indicated that WNT3A expression was significantly higher in BC tissues than in adjacent normal tissues and was even higher in the tumour tissues of patients with lymph node metastasis than in those without." (PMID 40099939, 2025).
renal cell carcinoma (5 papers, 2021 to 2023). "In conclusion, knockdown of PDIA6 suppressed cell proliferation and DNA damage repair of imatinib-resistant renal cell carcinoma cell and promoted the cell apoptosis through down-regulation of Wnt3a and FZD1." (PMID 34781823, 2021). "Additionally, APOC1 represents a novel diagnostic marker for clear cell renal cell carcinoma and stimulates renal cell carcinoma through Wnt3a/STAT signaling." (PMID 37305534, 2023). "Silencing of PDIA6-induced decreases in p-DNA-PK and Rad51 was restored by over-expression of FZD1, suggesting that PDIA6 might contribute to the resistance of renal cell carcinoma to imatinib through activation of Wnt3a/FZD1 pathway." (PMID 34781823, 2021). "Moreover, apolipoprotein C1 promoted Wnt3a to stimulate progression of renal cell carcinoma." (PMID 34781823, 2021). "Lastly, protein expression levels of Wnt3a and Frizzled1 (FZD1) in imatinib-resistant renal cell carcinoma cells were down-regulated by silencing of PDIA6." (PMID 34781823, 2021).
cholangiocarcinoma (4 papers, 2016 to 2025). A carcinoma that arises from the intrahepatic biliary tree (intrahepatic cholangiocarcinoma) or from the junction, or adjacent to the junction, of the right and left hepatic ducts (hilar cholangiocarcinoma). "Since the Wnt/β-catenin signaling pathway was previously reported as a vital regulatory factor in cholangiocarcinoma, the key pathway-related proteins, including Wnt3a, phosphorylated GSK3β, and β-catenin, were detected in HCCC-9810 cells after FOXP1 overexpression or knockdown." (PMID 38279090, 2024). "Moreover, WNT3a treatment significantly reduced the sensibility of cholangiocarcinoma QBC939 cells to chemotherapeutics." (PMID 27391060, 2016).
colorectal tumor (4 papers, 2014 to 2022). "WNT3A was found to be overexpressed and correlated with the level of MMP9 in colorectal tumor tissues." (PMID 31850854, 2019). "Based on this backdrop, our present study revealed that colorectal tumors respond to FOFOX therapy by stimulation of supporting CAFs in the tumor-microenvironment to provide cues in the form of secreted factors (PN and IL17A) to stimulate WNT3A signals to maintain CICs." (PMID 35982950, 2022).
cyst (4 papers, 2015 to 2023). A sac-like closed membranous structure that may be empty or contain fluid or amorphous material. "Wnt3a administration induced Rab8a+/+ organoids into a cyst-like morphology, an effect that was also observed for Rab8a-deficient organoids." (PMID 26015543, 2015). "Our results showed that Wnt3a was indispensable for the growth of cyst-enriched organoids." (PMID 37495742, 2023). "In our study, the cyst formation media contained 4 soluble factors and 2 signal inhibitors such as EGF, HGF, Wnt3a, R-spondin-1, ROCK inhibitor Y-27632, and TGF-β inhibitor A-8301." (PMID 27335264, 2016). "Therefore, Wnt3a, FGF-2, and Y-27632 are critical components for culturing cyst-enriched organoids." (PMID 37495742, 2023).
diabetes (4 papers, 2021 to 2023). "Wnt3a/β-catenin signaling pathways in diabetes enhances the production of several growth factors involved in the initiation and maintenance of the healing process while reducing the inflammatory response." (PMID 35737691, 2022). "In conclusion, the results demonstrated that GC-AgNPs-CGP (CGP2 & CGP3) dressing on diabetes wound rats decreased changes in Wnt3a/β-catenin pathways, resulting in lower apoptosis and greater proliferation, so drastically improving diabetic wound healing." (PMID 35737691, 2022). "Besides the regulatory role of NF-kappaB in inflammation and oxidative stress in diabetes, wnt3a/β-catenin was also reported to be involved in these processes." (PMID 34607529, 2021).
esophageal cancer (4 papers, 2019 to 2022). A primary or metastatic malignant neoplasm involving the esophagus. "In this study, using public databases and our clinical cohorts, we found the genes IGFBP1 and WNT3A from WNT signaling, which are closely associated with immunotherapy for esophageal cancer." (PMID 36358276, 2022). "Heatmaps showed the relationship between RNF168 and WNT3A expression and survival in 184 patients with esophageal cancer." (PMID 33493132, 2021).
ischemic stroke (4 papers, 2021 to 2025). A stroke disorder caused by obstruction of blood flow to the brain, due to thrombotic (local blood clot formation) or embolic (due to a blood clot or other material traveling from another site) event. "Following rESWT, there was an upsurge in the protein and gene expression levels of Wnt3a and β-catenin in the brains of rats with ischemic stroke." (PMID 38777838, 2024). "Wnt3a promotes BBB integrity and neurogenesis and its downregulation is associated with BBB leakage and neuroinflammation in traumatic brain injury and ischemic stroke." (PMID 41156605, 2025).
keloid (4 papers, 2017 to 2022). An irregularly shaped, elevated mark on the skin caused by deposits of excessive amounts of collagen during wound healing. "In a previous study, we demonstrated that the EMT-like transition via Wnt3a activation substantially contributes to collagen accumulation during the development of keloids." (PMID 29283384, 2017). "As previously reported, these data suggest that Wnt3a and its effector β-catenin protein are actively expressed in keloid tissues." (PMID 29118355, 2017). "Both Wnt3a and β-catenin expression levels from keloid tissues were markedly higher by 3.9- and 2.9-fold, respectively, in comparison to extra-lesional normal tissue." (PMID 29118355, 2017). "Higher Wnt3a and β-catenin expression was observed in the keloid region compared to the adjacent normal tissues." (PMID 29118355, 2017). "In present study, we confirmed that both Wnt3a and β-catenin proteins are overexpressed in human primary keloid tissues, suggesting that Wnt signaling pathway may be involved in regulation of collagen expression in keloids." (PMID 29118355, 2017). "Thus, Wnt-3a-mediated EndoMT may contribute to the excessive dermal fibrosis that characterizes keloids." (PMID 32268503, 2020). "Thus, they first showed that keloid tissues expressed high levels of Wnt-3a." (PMID 32268503, 2020). "The results showed that the expression of Wnt3a, β-catenin, and S100A4 proteins in keloid was significantly higher than that in normal skin (p < 0.05)." (PMID 36263010, 2022). "The decreased levels of Wnt3a and TGF-β1 in keloid tissue explants treated with dEl-k35/sLRP6E1E2 was reduced by 91% and 43%, respectively, in comparison to dE1-k35/LacZ-treated keloid tissue explants." (PMID 29118355, 2017).
myocardial infarct (4 papers, 2018 to 2025). "Furthermore, supplementation of Wnt3a can reduce the size of infarction areas after myocardial infarction." (PMID 35936906, 2022). "Therefore, our data on the increase in apoptosis as well as wnt3a and β-catenin activity is in agreement with the published myocardial infarction model and provides novel information in Dox-induced muscle toxicity." (PMID 30151071, 2018). "Additionally, wnt3a has been published in previous studies of myocardial infarction-induced apoptosis, where increased levels of wnt3a were observed after the infarct was generated, whereas sFRP2 administration attenuated this wnt3a activity." (PMID 30151071, 2018).
periodontitis (4 papers, 2021 to 2025). An acute or chronic inflammatory process that affects the tissues that surround and support the teeth. "The experimental induction of periodontitis in rats, by drilling the first molar until the exposure of the pulp, is associated with higher Wnt3a and β-catenin." (PMID 40421179, 2025). "Expression of Wnt3a and β-catenin correlates with the volume of the periodontitis-induced lesion, suggesting that activation of the Wnt/β-catenin pathway associates with periodontitis progression." (PMID 40421179, 2025). "Studies that have shown the relevance of Wnt ligands inducing the Wnt/β-catenin pathway during periodontitis progression, are mainly focused on Wnt3a." (PMID 40421179, 2025). "For instance, gingival tissues from patients with stage 3 periodontitis display higher Wnt3a, Wnt10b and nuclear β-catenin immunohistochemical staining, indicating the participation of the Wnt/β-catenin in periodontitis." (PMID 40421179, 2025). "Together, it was found that Wnt ligands Wnt3, Wnt3a, Wnt5b and Wnt7b are concomitantly upregulated in periodontitis and oral carcinogenesis." (PMID 40421179, 2025). "By analyzing the GEO databases GSE223924 and GSE85195 we found that the Wnt ligands Wnt3, Wnt3a, Wnt5b and Wnt7b are transcriptionally upregulated in periodontitis and OSCC, especially during early carcinogenic phases." (PMID 40421179, 2025). "The further PPI analysis has revealed some of genes play a key role in pathogenesis in periodontitis, including WNT3A, BMP2, CXCL12 and PI3KR2." (PMID 35491409, 2022). "Further investigation revealed that siRNA‐mediated silencing of Nedd4‐2 in P. gingivalis‐stimulated PBMCs resulted in increased protein expression of Wnt3a, an anti‐inflammatory regulator that plays a significant role in controlling inflammation and bone metabolism in periodontitis." (PMID 39626954, 2025). "Interestingly, the transcriptional upregulation of Wnt3, Wnt3a, Wnt5b and Wnt7b in periodontitis (GSE223924) was also observed in oral carcinogenesis (GSE85195)." (PMID 40421179, 2025). "This study further explored the upstream regulators of Nedd4‐2 and demonstrated that Janus Kinase 3 (JAK3) amplified Wnt3a signalling by phospho‐inactivating Nedd4‐2, thereby suppressing the infiltration of inflammatory cells in P. gingivalis‐induced mice with periodontitis." (PMID 39626954, 2025). "In a study on periodontitis of rat model, the researchers found that Wnt3A activity was decreased." (PMID 35491409, 2022). "In the periodontitis, the activated Wnt3A contributed to the inflammatory response." (PMID 35491409, 2022). "Among these four Wnt ligands, mRNA levels of Wnt3a, Wnt5b and Wnt7b are upregulated in leukoplakia and early stage OSCC, suggesting that if a causality is determined between periodontitis and OSCC, these ligands may participate in initiating malignant transformation of normal oral cells." (PMID 40421179, 2025). "Thus, in periodontitis pathology, the decreased expression of Wnt3A could affect the repair of bone by restriction on bone formation." (PMID 35491409, 2022). "More interestingly, some of these key genes also play a role in the pathology of peri-implantitis, such as WNT3A, PI3K, BMP2, which indicated the interaction between periodontitis and peri-implantitis." (PMID 35491409, 2022). "Transcriptomic Z-score analysis shows that among 19 Wnt ligands available, two canonical Wnt ligands (Wnt3 and Wnt3a) and two non-canonical Wnt ligands (Wnt5b and Wnt7b) are upregulated in periodontitis." (PMID 40421179, 2025).
prostate tumors (4 papers, 2013 to 2024). "Recently, WNT3A, which promotes tumorigenesis via accelerated cellular proliferation and invasion, is found to be directly regulated by the miR-15a/16-1 cluster, and upregulation of WNT3A is inversely correlated with decreased miR-15a and miR-16-1 in advanced prostate tumors." (PMID 27195958, 2016).
renal fibrosis (4 papers, 2014 to 2024). A final common manifestation of a wide variety of chronic kidney diseases characterized by glomerulosclerosis and tubulointerstitial fibrosis. "Furthermore, the in vivo experiments confirmed that JPYSF effectively ameliorated interstitial fibrosis and inhibited the overexpression of α-SMA, Wnt3a, and β-catenin, and increased the expression of E-cadherin by wnt3a/β-catenin signaling pathway in 5/6 Nx-induced renal fibrosis rats." (PMID 35656312, 2022). "Activation of WNT3a/β-catenin signaling pathway has been observed to induce phosphorylation and nuclear translocation of STAT3, which in turn has been demonstrated to aggravate macrophages M2 polarization and promote the process of renal fibrosis." (PMID 40012992, 2024).
retinoblastoma (4 papers, 2010 to 2022). A malignant tumor that originates in the nuclear layer of the retina. "From the results that overexpression of miR‐361‐3p can inhibit retinoblastoma progression by binding to WNT3A, the circDHDDS/miR‐361‐3p/WNT3A axis is a potential pathway." (PMID 35592755, 2022). "LiCl was used in this study because it had a greater phenotypic effect on retinoblastoma cell lines than the canonical Wnt ligand Wnt3a." (PMID 20069066, 2010). "LiCl was used in this study because it had a greater effect on cell cycle arrest and viability in the retinoblastoma cell lines than the canonical Wnt ligand Wnt3a." (PMID 20069066, 2010). "Furthermore, circular RNAs (circRNAs) can also serve as ceRNAs to regulate the proliferation and migration of retinoblastoma cells, such as the circDHDDS/miR-361-3p/WNT3A axis and Circ_0000034/miR-361-3p/ADAM19 axis." (PMID 34095180, 2021).
rheumatoid arthritis (4 papers, 2022 to 2026). A chronic, systemic autoimmune disorder characterized by inflammation in the synovial membranes and articular surfaces. "The occurrence and development of rheumatoid arthritis (RA) are closely related to bone erosion caused by the abnormal activation of the Wnt3a/β-catenin signaling pathway." (PMID 40936889, 2025). "Our results show that monocytes of patients affected with psoriatic arthritis and rheumatoid arthritis (referred to in this paper as RJD) react differently to Wnt-3a stimulus in terms of chemokine and cytokine expression." (PMID 38622714, 2024). "In addition, miR-708-5p promotes the apoptosis of synoviocytes, fibroblast-like cells, and eases rheumatoid arthritis by suppressing the Wnt3a/β-catenin pathway." (PMID 35456388, 2022).
asthma (3 papers, 2019 to 2026). "The Wnt/β-catenin pathway, activated by WNT3A, has been linked to inflammatory processes in various diseases, including asthma and possibly AR." (PMID 39329917, 2024). "This activation could contribute to the recruitment of immune cells in conditions associated with increased Wnt-3a expression, such as asthma." (PMID 31683769, 2019). "Thus, our data suggest that Wnt-3a activation of mast cells could contribute to the recruitment of immune cells in conditions associated with increased Wnt-3a expression, such as asthma." (PMID 31683769, 2019). "Consequently, researchers have proposed that the activation of mast cells by WNT3A may be effective in stimulating immune cells in diseases where WNT3A expression is increased, such as asthma." (PMID 39329917, 2024). "Furthermore, multiple Wnt genes (e.g., WNT3A, WNT5a, WNT6, and WNT10A) and the receptor FZD5 are positively correlated to a Th2 signature in the airways of humans with asthma." (PMID 31683769, 2019).
bladder cancer (3 papers, 2020 to 2025). "LINC00536, a newly identified lncRNA by Nakajima in 2014, was found to be highly expressed in bladder cancer and promoted the tumorigenesis and development of bladder cancer partly by modulating the Wnt3a/β-catenin signaling." (PMID 33194577, 2020).
breast tumor (3 papers, 2018 to 2024). "Antibodies inhibiting the interaction of LRP6 with Wnt1 or Wnt3a decrease breast tumor growth in Wnt1- and Wnt3a-driven xenografts, respectively." (PMID 29854300, 2018).